C1orf220 (chromosome 1 putative open reading frame 220)
Synonyms: FLJ35530
Gene: Long non-coding RNA gene on chromosome 1 (178,542,752 to 178,548,889, forward strand). Ensembl gene ENSG00000213057.
Diseases named in the same sentence as C1orf220 in open-access papers:
C1orf220 is named in the same sentence as 2 diseases in open-access papers, as found by Europe PMC text mining. Sharing a sentence is not in itself a finding about the gene and the disease. The quoted sentences say what the papers report.
lung adenocarcinoma (1 paper, 2022). A carcinoma that arises from the lung and is characterized by the presence of malignant glandular epithelial cells. "Hsa-mir-145 formed the third regulatory module for lung adenocarcinoma c with lncRNA C1orf220, which ranked second in potential lncRNAs, and mRNAs (COL1A2, COL3A1, SPP1, TIMP1 and CDH1)." (PMID 36138770, 2022).
lung squamous cell carcinoma (1 paper, 2022). "Bioinformatics studies have shown that C1orf220 plays an important role in central gene regulation of lung squamous cell carcinoma." (PMID 36138770, 2022).